MMP9 (matrix metallopeptidase 9)
Diseases named in the same sentence as MMP9 in open-access papers (continued):
Sharing a sentence is not in itself a finding about the gene and the disease.
ischemic stroke (continued). "MMP-9 levels can also be used to predict ischemic stroke and cardiovascular death in patients with 50% and more carotid stenosis." (PMID 35449607, 2022). "They identified 88 transcripts with a 1.5-fold change in ischemic stroke compared to controls and 11 transcripts with 2-fold difference (including MMP9, Il1R2)." (PMID 33633673, 2021). "Gelatin zymography showed that both MMP-2 and MMP-9 activities were significantly increased in the ipsilateral hemisphere following ischemic stroke." (PMID 34299128, 2021). "Given the fact that almost all pediatric patients present ischemic strokes, we further investigate MMP-9 in adult MMD subgroups and results showed, similarly, that hemorrhagic-type MMD patients had a higher level of MMP-9 than ischemic-type MMD patients." (PMID 34531816, 2021). "This is because, following an ischemic stroke, the levels of degenerative enzymes such as MMP‐9 increase in the brain, which are correlated with poor disability outcomes." (PMID 34105297, 2021). "Evidence of this was confirmed in vivo-studies that showed that MMP-2 and MMP-9 levels, intima-media thickness, and the stability of the plaques are strongly correlated with the ischemic stroke process." (PMID 34445740, 2021). "Leukocytes, mainly neutrophils, are an important source of MMP-9 that contributes to early disruption of the BBB in ischemic stroke." (PMID 33925459, 2021). "Serum MMP-9 concentrations ≥140 ng/ml were shown to predict hemorrhagic transformation in rt-PA treated ischemic stroke patients (sensitivity 92%, specificity 74%)." (PMID 33633673, 2021). "Activities of matrix metalloproteinase-2 and -9 (MMP-2 and MMP-9) significantly increased during ischemic stroke in both animal models and patients." (PMID 34299128, 2021). "In the current study, we found that high plasma MMP-9 levels were associated with VBE and predicted ischemic stroke in patients with vertigo or dizziness." (PMID 32982940, 2020). "In the acute phase of the ischemic stroke, there is a significant increase in MMP-9 expression in the ischemic area and a noticeable increase in peripheral blood concentration." (PMID 32575870, 2020). "Altogether, changes of the MMP-9 serum levels in the course of ischemic stroke are a signal of several pathophysiological processes, which determines its diagnostic value." (PMID 31701356, 2020). "NG-nitro-L-arginine methyl ester (L-NAME), a non-selective NOS inhibitor, attenuated the BBB disruption through inhibiting MMP-9 activity in an experimental ischemic stroke animal model." (PMID 32508671, 2020). "Single nucleotide polymorphisms have been found in several genes related to inflammation and ischemic stroke; these polymorphisms include the following: IL-1β, IL-6, IL-10, MMP-2, MMP-9, MMP-12, E-selectin, L-selectin, CD36, PCSK9, and adiponectin." (PMID 33153204, 2020). "A clinical trial investigated the relationship between antisense noncoding RNA in the INK4 locus (ANRIL) and high-sensitivity C-reactive protein (hs-CRP) and matrix metalloproteinase-9 (MMP-9) in blood serum of ischemic stroke patients." (PMID 33192490, 2020). "Our study shows for the first time that MMP-9 is an important downstream effector contributing to COX-2-mediated neurovascular damage in ischemic stroke." (PMID 32973660, 2020). "Increased levels of MMP-9 seem to be related to poorer outcomes and increased complications in ischemic stroke." (PMID 33520535, 2020). "MMP-9 has been extensively investigated and was highly upregulated in an animal cerebral ischemia model and in human ischemic stroke." (PMID 32908557, 2020). "MMP-9 levels can also be used to predict ischemic stroke and cardiovascular death in patients with > or =50% carotid stenosis." (PMID 33082709, 2020). "MMP-9 is associated with BBB breakdown and subsequent vasogenic edema, and an MMP-9 polymorphism was shown to confer susceptibility to ischemic stroke in a Chinese population." (PMID 32848875, 2020).
ischemic stroke (continued). "Compared to the Ischemia group, QKL treatment markedly downregulated MMP-9 which was activated by ischemic stroke." (PMID 32908557, 2020). "MMP-9 is a plasma biomarker for monitoring brain damage and predicting hemorrhagic transformation in ischemic stroke with thrombolytic treatment." (PMID 32508671, 2020). "In ROC analysis, MMP-9 had a significantly predictive effect on ischemic stroke (area under the curve, AUC = 0.582, 95%CI, 0.510–0.654, P = 0.030)." (PMID 32982940, 2020). "Previous studies have reported that MMPs, particularly MMP-9, were detected in the acute phase after ischemic stroke, coinciding with the opening of the blood–brain barrier, and partially contributing to the extent of the infarction." (PMID 32796743, 2020). "The prospective research should focus on the development of novel therapeutic modalities to mitigate the MMP-9 expression in ischemic stroke by modulating the expression of miR-21." (PMID 32937836, 2020). "Taken together, a large body of evidence suggests that MMP-9 is involved in COX-2/PGE2-mediated BBB damage in ischemic stroke." (PMID 32973660, 2020). "MMP-9 degrades tight junction proteins in a variety of neurological diseases, including ischemic stroke, traumatic brain injury, and SAH." (PMID 33732145, 2020). "The destruction of the blood–brain barrier has been identified as a potential mechanism for HT after ischemic stroke, and neutrophils have been shown to be an important source of MMP‐9, which can lead to early disruption of the blood–brain barrier in AIS." (PMID 31429525, 2019). "In the BBB, MMP-9 is primarily secreted from pericytes and is associated with BBB disruption in several diseases including ischemic stroke, intracerebral hemorrhage, hemorrhagic transformation, brain edema, Alzheimer’s disease and Parkinson’s disease." (PMID 31811815, 2019). "During ischemic stroke, endothelial cells overexpress MMP-9 within and at the periphery of ischemic lesions that results in increased vascular permeability." (PMID 31291966, 2019). "In humans, patients with ischemic stroke show higher levels of MMP-9 in the blood, and more importantly, MMP-9 levels are associated with a poorer prognosis." (PMID 30618576, 2018). "Previous data suggest that overexpression of metalloproteinases, especially MMP-9, after ischemic stroke disrupts the BBB by degrading the tight junctions and basal lamina proteins." (PMID 29929562, 2018). "It is noted that inhibition of MMP-9 provided robust protection against the BBB disruption, suggesting that MMP-9 was the dominant protease acting at the BBB following ischemic stroke." (PMID 29724240, 2018). "Both hemorrhagic and ischemic stroke induced the expression of MMP-9 in the brain tissue; meanwhile, MMP-9 mediated the breakdown of the BBB." (PMID 29551991, 2018). "The other group’s study indicated that the plasma concentrations of MMP-9 were significantly higher in either hemorrhagic or ischemic stroke patients than control participants." (PMID 29551991, 2018). "In human postmortem brain tissue, age positively correlated with neutrophil infiltration, MMP-9 expression, and hemorrhage after ischemic stroke." (PMID 29752550, 2018). "MMP-9 upregulated in the first 3 days after ischemic stroke contributed to BBB permeability and brain inflammation." (PMID 30237808, 2018). "Ischemic stroke induced matrixmetallo-proteinase-9 (MMP-9) upregulation, which increased blood-brain barrier permeability." (PMID 29724240, 2018). "Following ischemic stroke, the neurovascular unit is impaired, with increased MMP-9 activity degrading the basal lamina and tight junctions." (PMID 29963617, 2018). "Clinical and experimental studies demonstrated that matrixmetallo-proteinase (MMP-2, MMP-3, MMP-7, or MMP-9) was activated and upregulated after ischemic stroke." (PMID 29724240, 2018). "Together, genetic deletion of IRAK-M accentuated BBB disruption via the upregulated expression of MMP-2 and MMP-9 in the mouse model of ischemic stroke." (PMID 30622459, 2018).
ischemic stroke (continued). "In the clinic, MMP-9 is mainly derived from infiltrating neutrophils and microvessel endothelium after ischemic stroke in humans." (PMID 28690765, 2017). "MMP-9 is considered as the predominant protease which can break the integrity of BBB following ischemic stroke." (PMID 28690765, 2017). "As such, it is universally accepted that profound changes in MMP-9 expression and activity occur following ischemic stroke in both humans and animals." (PMID 26973468, 2016). "MMP-9 levels were also a good predictor of petechial hemorrhage (PH) in tPA-treated ischemic stroke patients." (PMID 26973468, 2016). "tPA has been shown to directly activate MMP-9, with rt-PA treatment increasing MMP-9 activity in the serum of ischemic stroke patients." (PMID 26973468, 2016). "In some studies higher circulating MMP-9 levels were found in ischemic stroke patients than in controls, and in ischemic stroke patients with worse functional outcome." (PMID 26162891, 2015). "The aim of the present study was to investigate the correlation between the −1562C/T polymorphism in an intron of the matrix metalloproteinase-9 (MMP-9) gene and hemorrhagic transformation of ischemic stroke (IS)." (PMID 25667675, 2015). "MMP-9 and MMP-3 have been implicated in neurovascular injury and apoptotic cell death in ischemic stroke, in both humans and rodent models." (PMID 26648273, 2015). "With respect to MMP-9’s role after cerebral ischemia, considerable research has proven that MMP-9 is up-regulated and activated after ischemic stroke and in animal models of I/R." (PMID 25844636, 2015). "Ischemic stroke (IS) and intracerebral hemorrhage (ICH) are both associated with activation and altered expression of MMPs, mainly MMP-2 and MMP-9." (PMID 26330106, 2015). "MMP-2 and MMP-9 released from the vascular endothelium and leukocytes during the inflammatory phase of ischemic stroke use collagen IV and laminin as substrates." (PMID 25280484, 2014). "Gene expression and plasma concentrations of MMP9 have been shown to be significant higher in ischemic stroke patients compared to healthy controls, and in severe sepsis." (PMID 24983946, 2014). "There is controversy regarding timing of brain MMP-9 expression and activation after ischemic stroke." (PMID 23565108, 2013). "Evidence suggests that MMP-2 and MMP-9 play different roles in BBB disruption during ischemic stroke." (PMID 23565108, 2013). "In a rat ischemic stroke model, pretreatment with atorvastatin and amlodipine ameliorated post-ischemic brain weight increase and induction of MMP-9." (PMID 23967318, 2013). "Elsewhere in this special issue, Yepes describes how TWEAK/Fn14 signaling in middle cerebral artery occlusion (a model of ischemic stroke) induces inflammation and MMP-9 mediated basal lamina disruption." (PMID 24400009, 2013). "During ischemic stroke, MMP-9 inhibition also mitigates BBB disruption and reperfusion injury experimentally induced by the thrombolytic agent tPA, a therapeutic agent that can itself increase the risk of bleeding." (PMID 22587708, 2012). "Elevated MMP-9 expression was observed within the first three days after ischemic stroke and it exhibited close connection with the extent of BBB breakdown." (PMID 22438957, 2012). "Of the two MMPs - 9 and 2 that are consistently reported to be up-regulated in ischemic stroke, we found MMP-9 to be the most strongly expressed in early ischemia reperfusion and later at 24 hours post reperfusion." (PMID 22742423, 2012). "There is abundant evidence indicating that increased MMP-9 expression after ischemia significantly contributes to basal lamina degradation, thus leading to hemorrhagic transformation of ischemic stroke." (PMID 21569344, 2011). "Although complete neutropenia can reduce the increased levels of MMP-9 after transient MCAo, it cannot entirely abolish the upregulation after ischemic stroke." (PMID 21040547, 2010).
ischemic stroke (continued). "Protein levels of MMP-9 increase in the blood early on after ischemic stroke onset, and this increase is enhanced by tPA." (PMID 20406488, 2010). "MMP-9 knock-out mice, on the other hand, do show better outcome after ischemic stroke, and inhibition of MMP-9 as late as 4 hours after ischemia onset decreases infarct size." (PMID 21040547, 2010). "Matrix metalloproteinases 2 and 9 (MMP-2 and MMP-9) are increased in the brain after experimental ischemic stroke in rats." (PMID 16846501, 2006). "The results of the mechanism study showed that the combination of AS-TMP could adjust the expression levels of TIMP-1 and MMP-9 in the animal serum and cortical brain tissue of rat models of ischemic stroke." (PMID 40869300, 2025). "MMP-9 is the most prevalent MMP member, ubiquitously expressed and released in brain and cerebrospinal fluid (CSF) of patients suffering from ischemic stroke, vascular dementia, AD, dolichoectasia, viral-associated neurocognitive disorders, neuro-Behcet’s disease and MS." (PMID 40332093, 2025). "TIMP-1 and MMP-9 are key factors closely related to BBB injury in ischemic stroke." (PMID 40869300, 2025). "This indicates that ischemic stroke triggers a massive upregulation of MMP-9 activity." (PMID 38255970, 2024). "In aged mice subjected to ischemic stroke, adropin treatment decreased infarct volume and brain edema and improved sensorimotor and cognitive functions by reducing Matrix metalloproteinase-9 (MMP-9) activity and preserving tight junction proteins." (PMID 39766320, 2024). "MMP2, MMP3 and MMP9 are critical MMPs involved in BBB opening after ischemic stroke." (PMID 37611902, 2024). "The neuroinflammatory response of MMP-9 in ischemic stroke has also been investigated." (PMID 39850789, 2024). "Currently, MMP-9 is considered a new target in ischemic stroke treatment." (PMID 39599732, 2024). "Understanding the temporal dynamics of MMP-9 activity could inform the development of therapeutic interventions targeting MMP-9 to modulate its effects during the different phases of ischemic stroke." (PMID 38255970, 2024). "Additionally, ischemic stroke triggers MMP activity, notably MMP-2 and MMP-9, implicated in BBB disruption and extracellular matrix degradation." (PMID 38872149, 2024). "Moreover, exploratory clinical trials focusing on ischemic stroke have demonstrated that inhibition of MMP‐9 markedly reduces the breakdown of the BBB and neural tissue damage." (PMID 38379112, 2024). "Previous studies have shown that naringenin could attenuated diabetic neuropathic pain by modulating the expression of MMP-9, and may have protective effect on ischemic stroke by down-regulating the expression of NOD2, RIP2, NF-κB, MMP-9." (PMID 37270490, 2023). "Of the MMPs, MMP-9 (gelatinase B) has been most prominently tied to BBB disruption following ischemic stroke degrading type IV and V collagens, which are significant components of the ECM’s basal lamina as well as tight junction proteins including occludin, claudins, and ZO-1." (PMID 38178909, 2023). "The authors demonstrated that the ischemia-induced upregulation of NF-κB and MMP9 were reduced following NOB injection, suggesting that NOB’s therapeutic impact in ischemic stroke may be linked to a lower expression of MMP9 and NF-κB genes." (PMID 35631419, 2022). "Matrix metalloproteinase-9 (MMP-9) is one of the most extensively studied circulating biomarkers in ischemic stroke because of its role in neuroinflammation, early vasogenic edema, neuronal apoptosis, vascular remodeling, and neurorepair during the ischemic stroke pathobiological process." (PMID 36092813, 2022). "For further verification, potential core targets (STAT3, MMP2, ESR1, TERT, and MMP9 proteins) for ischemic stroke and core active ingredients (Tanshinol A, Tanshinol B, Tanshinone II A, and Przewaquinone C) for Salvia miltiorrhiza Bge. were further verified by molecular docking." (PMID 36133785, 2022).
ischemic stroke (continued). "Our results suggested that a persistent increased level of circulating MMP-9 could reflect the brain tissue injury and cell death in the acute stage after ischemic stroke, which is related to the adverse outcomes rather than baseline expression." (PMID 36092813, 2022). "MMP‐9, a marker of HT events in ischemic stroke, was higher in the HG group than in the NG group." (PMID 34591349, 2022). "MMP-9 expression levels are low in normal brain tissue, but are increased after ischemic strokes." (PMID 35273556, 2022). "When administered with r-tPA, specific MMP-9 inhibitors markedly reduced brain hemorrhage, swelling, infarction, disability and death, suggesting that blocking the deleterious effects of MMP-9 may improve outcomes after ischemic stroke." (PMID 35163322, 2022). "AGNHW could be a potential adjuvant therapy with t-PA to protect the BBB integrity, reduce HT, and improve therapeutic outcome in ischemic stroke treatment via inhibiting peroxynitrite-mediated MMP-9 activation." (PMID 35477576, 2022). "MMP-9 plays a key role in the delayed opening of the BBB after ischemic stroke." (PMID 34612696, 2021). "Our study furthers the previous research on MMP-9 gene methylation, which is consistent with the observation that MMP-9 gene methylation is a relatively frequent event in sporadic ischaemic stroke and promoter methylation of MMP-9 gene plays a pivotal role in functional inactivation." (PMID 35002488, 2021). "In 130 patients with acute focal neurologic deficits admitted within 6 h of onset of symptoms, a panel including D-dimer, CRP, B-type natriuretic protein (BNP), MMP-9, and S100B was predictive of ischemic stroke with sensitivity and specificity of 81 and 70%, respectively." (PMID 33633673, 2021). "The actions and phases of MMP-2 and MMP-9 differ in the case of an ischemic stroke." (PMID 34299128, 2021). "pJNK, MMP-9, and c-Fos are important factors in the progression of ischemic stroke." (PMID 34201112, 2021). "In contrast, MMP-9 knockout provides strong protection in ischemic stroke mouse models." (PMID 33487119, 2021). "Besides, we also noticed that GSS treatment reduced MMP-3 and MMP-9 mRNA and protein expression 41, provoking us to investigate the anti-inflammation effects and its underlying molecular mechanism of GSS in ischemic stroke." (PMID 33867831, 2021). "Increased serum TIMP‐1 may be an adaptive physiological response to enhanced MMP‐9 activity, in order to regulate excessive proteolytic activity and maintain extracellular matrix homeostasis in the acute phase ischaemic stroke." (PMID 32431079, 2020). "In this study, we hypothesized that genetic deletion or pharmacological inhibition of COX-2 reduces BBB damage by reducing MMP-9 activity in a mouse model of ischemic stroke." (PMID 32973660, 2020). "It is worth noting that neutrophils have been shown to be an important source of MMP‐9 and may mediate HT through MMP‐9 in ischemic stroke." (PMID 32697441, 2020). "The main MMP related to the atherosclerotic process and ischemic stroke is MMP-9." (PMID 33153204, 2020). "In ischemic stroke, increased MMP-9 in the damaged brain is one of the significant causes of BBB breakdown; moreover, PAR-1 is a main receptor for thrombin-induced expression of MMP-9 and pathological changes in BBB breakdown." (PMID 31885791, 2019). "In addition, there is a strong correlation between MMP-9 and HMGB1 levels in ischemic stroke patients, which was associated with poor outcome." (PMID 31291966, 2019). "Moreover, the increase in matrix metalloproteinase-9 (MMP-9) during the inflammatory phase of ischemic stroke was related to HT, and a 24 h peak of MMP-9 occurred before PH." (PMID 31920933, 2019). "This study aimed to explore potential new drugs in the treatment of ischemic stroke by Connectivity Map (CMap) and to determine the role of luteolin on ischemic stroke according to its effects on matrix metalloproteinase-9 (MMP9) and PI3K/Akt signaling pathway." (PMID 30911000, 2019).